LGALS9 (galectin 9)
Diseases named in the same sentence as LGALS9 in open-access papers (continued):
Sharing a sentence is not in itself a finding about the gene and the disease.
cancer (continued). "Other immunoregulatory molecules in cancer-derived exosomes such as FasL, TGF-β, galectin-9 and HSP72 support the immune escape of cancer cells." (PMID 29228644, 2017). "Our analysis showed that AATF, LGALS3, and SRC are up regulated in 8/13 of cancer models, and CDC2L2, E2F6, LGALS9, PDCD8, RELB, TRADD, and TRAF2 in 7/13." (PMID 19402918, 2009). "Further, ligand–receptor interactions differed: never‐smokers exhibited CD27+ B cell interactions via LGALS9–HAVCR2/CD44/CD45 and ANXA1–FPR1/FPR2, whereas smokers utilized CD74‐CXCR4/CD44 pathways linked to cancer progression." (PMID 41377765, 2025). "In addition, galectin-9 also acts on Dectin-1 for M2 macrophage polarisation in protective responses and on protein VEGF for angiogenesis as pro-oncogenic roles in the cancer cells." (PMID 37371482, 2023). "Notably, VSIR, LGALS9, and TNFRSF14 are highly correlated with RARA-AS1 in 16 types of cancer, indicating their potential as therapeutic targets." (PMID 37833349, 2023). "Our results revealed that in GBM cancer cells, expression of CD274 (PD-L1), PDCD1LG2 (PD-L2), LGALS9 (Galectin-9), and PVR (CD155) were positively correlated with the expression of multiple m6A regulators, especially YTHDF2, YTHDF3, LRPPRC, METTL3, RBM15B, FTO, and ALKBH5." (PMID 35558067, 2022). "While CD276, ENTPD1, IDO1, LGALS9, and VSIR were commonly detected in the Stereo‐seq samples, only IDO1 and LGALS9 seemed to have higher and wider expression in the CSCC samples than in the non‐cancer samples." (PMID 35986392, 2022). "Cell-free derivatives from NK cells are also being considered for cancer and viral immunotherapy, and our study highlights two main mediators of IFNα-NK antiviral response that could be exploited for treatment: IFN-γ and galectin-9." (PMID 35891518, 2022). "The co-expression of galectin-9 and TIM-3 has been detected in various types of cancer." (PMID 36140182, 2022). "Moreover, recent study suggests that Galectin-9 interacts with PD-1 and TIM-3 to regulate T cell death, making it a promising target for cancer immunotherapy." (PMID 35479097, 2022). "Here, we confirmed that soluble VISTA on its own (in the absence of galectin-9) prevents release of granzyme B from cytotoxic T cells into target cancer cells." (PMID 35634346, 2022). "Notably, in GBM cancer cells, CD274 (PD-L1), PDCD1LG2 (PD-L2), LGALS9 (Galectin-9), and PVR (CD155) were correlated with m6A regulators." (PMID 35558067, 2022). "Moreover, for FCER1G, LGALS9, TWEM149, EVI2B, and HAMP, the gene expression levels in the cancer population were higher than those in the normal population." (PMID 32903590, 2020). "Many types of cancer cells express significantly higher amounts of galectin-9 compared to non-malignant cells of similar origin." (PMID 33295886, 2020). "Exposure of these cells to increasing concentrations of TGF-β for 24 h led to a clear induction of galectin-9 expression, suggesting differential responses of cancer/embryonic and non-malignant mature human cells." (PMID 33295886, 2020). "Of all cancers tested, PDAC showed the highest expression of LGALS9 (galectin-9) mRNA." (PMID 32055023, 2020). "Human cancer cells in most cases express higher levels of galectin-9 compared to non-transformed cells." (PMID 33295886, 2020). "According to in vitro work, the cell surface receptor for galectin-9 in cancer apoptosis has not been identified, and intracellular pathways processed in apoptosis remain to be thoroughly investigated." (PMID 28045432, 2017). "Additionally, cancer-derived EVs included several types of immunoregulatory molecules, such as FasL, TGF-β, NKG2D ligands, galectin-9, and HSP72, to support the immune escape of cancer cells." (PMID 27582126, 2017).
cancer (continued). "Ligand LGALS9 with its receptors (CD44, CD47, and HAVCR2) showed that the inflammatory meta program also interacted with immune cells, implying that it is a cysteine/galactose binding protein that can compromise the functions of NK and T cell to facilitate cancer cell immune escape." (PMID 38944814, 2024). "Galectin-9 inhibits ESCC and EAC cell proliferation mainly through inducing apoptosis, while heat shock protein 60 (Hsp60) and IL-8 axis may promote apoptosis resistance in cancers." (PMID 37047155, 2023). "However, the exact pharmacokinetics of galectin-9 in humans and the cell surface receptors involved in the induction of cancer apoptosis by galectin-9 have not been identified in previous studies." (PMID 37047155, 2023). "In addition, the cell surface receptors involved in galectin-9-induced apoptosis of cancer cells have not been identified, and the intracellular pathways involved in apoptosis have not been fully investigated." (PMID 37047155, 2023). "In cancer, multiple inhibitory checkpoints may be modulated, including programmed death ligand-1/2 (PD-L1/2), CD47, Galectin 9, and TNFRSF6B, for which ligands expressed on T cells or APCs may act synchronously or sequentially to promote overall suppression of the immune responses." (PMID 31750244, 2019). "LGALS9 preferentially kills T cells rather than cancer cells may assist cancer immune escape." (PMID 34660693, 2021). "We found that in all types of human cancer cells and in HEK293, TGF-β upregulated the amounts of expressed galectin-9 but not Tim-3." (PMID 33295886, 2020).
infection (82 papers, 2010 to 2026). The state of being infected such as from the introduction of a foreign agent such as serum, vaccine, antigenic substance or organism. "We identified the sequence encoding galectin-9 from Pagrus major and subsequently investigated the molecular characteristics and changes in gene expression patterns in response to artificial infection with major pathogens." (PMID 33440635, 2021). "Furthermore, strong associations between sCD40 and Galectin-9 with suPAR defined the Omicron variant infections, while the positive match of sCD40 with sTREM-1 serum levels characterized the Delta-infected patients." (PMID 39376569, 2024). "Moreover, some studies reported the association of Galectin-9 and the balance between infection/rejection in kidney transplantation and it has been postulated its immunoregulatory role during the ongoing cytotoxic response." (PMID 33942129, 2021). "We observed elevated levels of galectin-9 in the serum of active TB patients, consistent with reports indicating that cleaved galectin-9 levels in the serum serve as a biomarker for severe infection." (PMID 39495223, 2024). "In most of these cases, plasma galectin-9 levels reflected not only the presence of infection but also its severity." (PMID 39822268, 2024). "This emphasizes the relevance in MTO and galectin-9 biomarkers for assessing infection outcomes and their progression rates." (PMID 39822268, 2024). "APOL1 and CMPK2 are mainly induced by interferon and proinflammatory cytokines, and LGALS9 is widely expressed in cells and immune system tissues and plays a major role in the inflammatory response and immune response against infection." (PMID 37112994, 2023). "Microglia and monocytes/macrophages expressed Lgals9 (Galectin-9) in uninfected mice, but expression levels were higher following infection with JHMV and persisted to day 21 p.i. in spinal cords." (PMID 32999036, 2020). "Elevated levels of galectin-9 (Gal-9) in natural human infections have been documented in numerous reports." (PMID 28788062, 2017). "Although the level varies, the increased expression or production of galectin-9 can be observed following the infection of a variety of tissue cells and immune effector cells." (PMID 28991189, 2017). "Among the signals from macrophages to LZ GC B cells and memory B cells, the Lgals9-Ighm/Cd45 signaling showed a greater enhancement by PCV2 infection, while those signals that were originally stronger in the control group, such as Ptprc-Cd22, Cd52-Siglecg, and App-Cd74, were weaker." (PMID 41011514, 2025). "Further studies will determine precisely how SIV and other infection may induce increased production of galectin-9." (PMID 39822268, 2024). "The results revealed that binding of FOXO1 to the upstream promoter of Lgals9 was enhanced post-infection, suggesting that FOXO1 could directly bind to the Gal-9 promoter and suppress its transcriptional expression following T. gondii infection." (PMID 38987795, 2024). "Galectin-9–Tim-3 interaction has been shown to provide resistance against infection with HIV-1, which might play a beneficial role in terms of HIV-1 control in individuals on long-term ART." (PMID 37569647, 2023). "Tim-3 itself and its ligand Galectin-9 both have been shown to be upregulated by infection." (PMID 37675103, 2023). "Importantly, the percentage of infection further increased when both galectin-9 and IFN-γ were concomitantly neutralized (5D)." (PMID 35891518, 2022). "Moreover, to establish galectin-9 as a potential drug to fight infection, we aim to investigate the effects of its cross-linking with other antigens and immune cell types in vivo." (PMID 35891518, 2022). "Additionally the increased Lgals9 signals from neutrophils to T cells that we identified in primary infection could negatively regulate Th1 immunity via induction of cell death and suppression of cytokine expression." (PMID 40736456, 2025).
infection (continued). "Galectin-9 binds to ACE2, inhibiting SARS-CoV-2 entry, reducing cell infection in vitro, and improving animal survival." (PMID 41516283, 2025). "Regardless of these differences, there remained a direct correlation between MTO and galectin-9 during the acute and late phases, with the exception of animals with SIV0302-2 during late stage infection." (PMID 39822268, 2024). "For instance, Gal-9 (LGALS-9), which has been related to response infection is strongly over-expressed." (PMID 31487323, 2019). "The gene expression levels of galectin 9, TRIM 16 and TRIM 25 were all used as a measure of an appropriate response by the fish host to ISAv infection." (PMID 30650077, 2019). "This is supported by the observation of the decrease in intracellular Gal-9, as well as a decrease in LGALS9 expression, after infection." (PMID 28788062, 2017). "Thus, while there was limited data on increased MTO during the acute phase of SIV infection, we were still able to test if galectin-9 correlated with MTO during acute and late phase infection." (PMID 39822268, 2024). "We overexpressed gene LGALS9 in THP-1 cells by lentiviral packaging and infection." (PMID 38610007, 2024). "Although it is possible that CXCL-10 can be elaborated in the skin in the absence of obvious inflammation, elevations of Galectin-9 are not reported to occur in this setting and are typically seen when there is chronic inflammation or infection." (PMID 36765391, 2023). "We hypothesized that galectin-9 might bind to HCV virions through its carbohydrate-binding region, thus preventing viral entry into host cells and infection." (PMID 35891518, 2022). "We speculated that galectin-9 might act extracellularly to inhibit HCV binding to host cells and downstream infection." (PMID 35891518, 2022). "Importantly, the concomitant neutralization of both galectin-9 and IFN-γ significantly suppressed the antiviral response of IFNα-NKs and restored the infection." (PMID 35891518, 2022). "Galectin-9 is a non-membrane bound soluble lectin which is up-regulated during ISAv infection of ASK cells in vitro and is thought to play a role in the regulation of a diverse array of immune functions." (PMID 30650077, 2019). "Prior to infection, we confirmed the conversion of part of the Caco-2 cells to M-like cells by demonstrating the expression of galectin-9 on M-like cell surface but not on Caco-2 cells." (PMID 28178312, 2017). "However, in galectin-8−/− macrophages, but not in galectin-3−/− or galectin-9−/− macrophages, Mtb was not controlled at 24 h postinfection, and bacterial burdens were significantly higher throughout the course of infection." (PMID 34225486, 2021). "Importantly, serum levels of galectin-9 were found to significantly correlate with the levels of several pro-inflammatory mediators, such as IL-1α, IL-8, IFN-γ-inducible protein 10, and vascular endothelial growth factor, during the critical phase of infection." (PMID 28991189, 2017). "Without resolution of infection during late stage SIV infection, MTO and plasma galectin-9 keep increasing until medical cull is required based on declining animal health condition." (PMID 39822268, 2024).
infectious disease (11 papers, 2016 to 2024). A disorder directly resulting from the presence and activity of a microbial, viral, or parasitic agent in humans. "Galectin-9 (Gal-9) is a β-galactoside-binding lectin capable of promoting or suppressing the progression of infectious diseases." (PMID 33804076, 2021). "INR patients, who showed higher frequency of infectious diseases in our study, had significantly lower Galectin-9 levels than both the viremic groups." (PMID 32678033, 2020). "Galectin-9 plays an important role in many inflammatory and infectious diseases." (PMID 37569647, 2023).
bacterial infections (10 papers, 2015 to 2025). "In addition, high expression of galectin-9 and galectin-3BP was also observed in bacterial infection and OFI groups." (PMID 27240351, 2016).
immune diseases (8 papers, 2016 to 2025). "Moderate to high expression of Lgals9 in ChP suggested its various roles in ChP associated immune diseases and indeed Lgals9 function has been widely documented in the immunological responses." (PMID 28018170, 2016). "Galectin-9 is considered a marker of severity of a variety of immune diseases and acute and chronic infectious diseases, including COVID-19 disease." (PMID 37881427, 2023).
hematologic malignancies (6 papers, 2017 to 2025). "In hematological malignancies, galectin-9 was implicated in the suppression of antitumor immunity by T cell exhaustion via the galectin-9/Tim-3 axis in murine AML models." (PMID 29179486, 2017). "We also discuss the basic research and ongoing clinical trials on emerging immune checkpoints (Galectin-9/Tim-3, CD70/CD27, LAG-3, and LILRBs) and on new targets for CAR-T cell therapy (CD22, CD33, CD123, BCMA, CD38, and CD138) for the treatment of hematologic malignancies." (PMID 31186046, 2019).
inflammation (6 papers, 2017 to 2024). Aberrant reaction of the microcirculation characterized by movement of fluid and leukocytes from the blood into extravascular tissues. "Galectin-9, which is associated with liver inflammation through galectin-9/Tim-3 interaction, contributes to the expansion of the mTregs that are mainly originated from natural Tregs." (PMID 29127350, 2017). "The role of galectin-9 in retinal inflammation remains poorly understood and potential benefit of targeted therapeutic intervention merits further investigation." (PMID 39198470, 2024).
cardiovascular disease (2 papers, 2023 to 2024). "Immunomodulatory proteins have been demonstrated to play a role in the development and progression of cardiovascular diseases, including galectin-1, galectin-9, and alpha-1-microglobulin." (PMID 39767748, 2024). "Our findings corroborate the literature regarding the important roles of galectin-1, galectin-9, and alpha-1-microglobulin in cardiovascular diseases." (PMID 39767748, 2024). "Our results encourage further in-depth analyses of the possible interactions of LGALS9 as well as studies of their implications in signalling cascades, especially in the pathogenesis of cardiovascular disease." (PMID 38248876, 2023). "Taken together, these findings explain the biological mechanisms through which galectin-1, galectin-9, and alpha-1-microglobulin are related to cardiovascular disease progression, and therefore, may act as prognostic biomarkers for MACE in patients with PAD." (PMID 39767748, 2024).
gastrointestinal tumors (1 paper, 2022). "The upregulation of expression of caspase-cleaved keratin 18 (CCK18, a marker of cell apoptosis) is one of the characteristics of Galectin-9 in regulating the proliferation of various gastrointestinal tumors." (PMID 36358792, 2022). "Galectin-9 mainly plays a role in growth regulation in gastrointestinal tumors, characteristically by upregulating CCK-18." (PMID 36358792, 2022). "Galectin-9 exerts a proliferation regulation role in various gastrointestinal tumors." (PMID 36358792, 2022).
LGALS9 also shares sentences with these, for which no sentence is quoted: triple-negative breast carcinoma (7 papers); pulmonary TB (6); renal cell carcinoma (6); kidney diseases (5); pneumonia (5); Bladder cancer (4); diffuse large B-cell lymphoma (4); hematological cancers (4); lung adenocarcinoma (4); parasitic infections (4); psoriasis (4); abortion (3); B cell lymphoma (3); coagulopathy (3); coronary artery stenosis (3); emphysema (3); eosinophilic pneumonia (3); gastrointestinal stromal tumor (3); hepatitis B (3); inflammatory bowel disease (3); interstitial lung disease (3); juvenile dermatomyositis (3); large cell neuroendocrine carcinoma (3); Miscarriage (3); multiple myeloma (3); respiratory disease (3); rheumatic disease (3); serous ovarian carcinoma (3); steatosis (3); viral diseases (3).
A further 140 diseases each share a sentence with LGALS9 in 2 papers or fewer.